EGFR (epidermal growth factor receptor)
Diseases named in the same sentence as EGFR in open-access papers (continued):
Sharing a sentence is not in itself a finding about the gene and the disease.
melanoma (continued). "This suggests it may be possible to treat ErbB4-dependent melanomas using anti-EGFR and -ErbB2 therapies, particularly small molecule EGFR and/or ErbB2 tyrosine kinase inhibitors." (PMID 33378376, 2020). "Introduction of miR-7 decreases the expression levels of EGFR, IGF-1R, CRAF in vitro as well as in Vemurafenib-resistant cells in melanoma xenograft mice models, which indicates that EGFR, IGF-1R, and CRAF are the target genes of miR-7 that are associated with the acquired resistance to BRAFi." (PMID 32054078, 2020). "Conversely, Gal-1 overexpression could trigger this signaling circuit, promoting the upregulation of NRP1 and that of its downstream target EGFR in parental melanoma cells." (PMID 32784465, 2020). "We also investigated the correlation of the seven prognostic-associated TBCs between MMP-related genes (MMP2, MMP9, MMP7, MMP14, BSG, EGFR, MMP1, MMP3) and EMT-associated genes (TWIST1, VIM, CDH2, ACTA2, ZEB1), which also indicated a central role of TBCs in melanoma." (PMID 33194704, 2020). "The confirmation of a crosstalk between these pathways could provide a potential target for combinatorial therapeutic strategies for BRAF-mutant melanoma either at the level of EGFR and/or PGE2 production." (PMID 31819183, 2020). "The inhibitory profile of 7h against a panel of patient-derived tumor cell lines was established, demonstrating selective growth inhibition of EGFR related cells at 10 μM among a panel of 30 cell lines derived from colon, melanoma, breast, bladder, kidney, prostate, pancreas and ovary tumors." (PMID 30626888, 2019). "Our findings also could implicate that EGFR + BRAF + MEK combination therapy might improve efficacy of targeted therapy also in melanoma patients." (PMID 31514305, 2019). "FGFR3 may also promote the growth of melanoma through the EGFR signaling pathway by stimulating the phosphorylation of EGFR." (PMID 31619201, 2019). "Activation of the EGFR pathway was also identified in BRAF-inhibitor-resistant melanoma." (PMID 31514305, 2019). "Cetuximab was used as a positive control, on MCSP+EGFR+CD20- A375 melanoma cells." (PMID 30429531, 2019). "Therefore, in this work we focused on the analysis of direct involvement of EGFR or MET in the regulation of invasiveness of melanoma cells derived from primary tumour and metastasis." (PMID 31638339, 2019). "Importantly, melanoma cells with higher EGFR expression were more resistant to the EGFR inhibitor erlotinib treatment than cells with lower expression, with respect to both proliferation and migration inhibition." (PMID 31514305, 2019). "However, our present data showed that EGFR expression was hardly detected in melanoma cells, which is in consistent with previous studies." (PMID 30804329, 2019). "Our transcriptomic analysis showed that loss of SIRT2 in both P/VG and metastatic melanoma cell lines was associated with decreased expression of EGFR and EPHA2, receptors that are important for the development, proliferation and acquisition of multidrug resistance by melanoma cells." (PMID 31091806, 2019). "Overexpression of EGFR often occurs in advanced stage of melanoma." (PMID 31649529, 2019). "Together, the EGFR/ERK pathway may be responsible for LRIG1-mediated melanoma cell aggressive metastasis upon hypoxia by regulating cell invasion, migration, and VM via EMT." (PMID 30487162, 2019). "Moreover, the amplification of microphthalmia-associated transcription factor (MITF) gene seems to play a role in melanoma progression, while the role of the genomic amplification for EGFR and cMET genes is less clear." (PMID 29492214, 2018). "For this reason, we advance the hypothesis that the activation of the EGFR is a necessary event that allows the ignition and progression of the autophagic process, at least in melanoma cells." (PMID 30100990, 2018).
melanoma (continued). "However, our previous studies and others reported that endogenous Swiprosin-1gene expression was specifically upregulated in human mast and T cells up on PMA or A23187 or PMA/A23187 stimulation and also in malignant melanoma cells upon EGFR stimulation." (PMID 30405162, 2018). "In many melanoma cases, EGFR and MET are overexpressed or upregulated as a result of gene mutation." (PMID 29719603, 2018). "In many types of cancer, including melanoma, HER2 and EGFR are often upregulated or mutated." (PMID 29719603, 2018). "Interestingly, in the melanoma cell line, the EGFR phosphorylation was uncoupled with ERK1/2 phosphorylation, which we believe is due to the B-RAF (V600E) mutation in this cell line." (PMID 30416678, 2018). "Prerequisite for development of this mechanism of drug resistance is the upregulation of EGFR, since melanoma cells devoid of EGFR expression are sensitive to vemurafenib, lacking this feedback activation, and the ectopic expression of EGFR induces resistance to PLX4032 in melanoma cells." (PMID 29033690, 2017). "Thus, in melanoma, one sample (6.2%) had an uncommon BRAF (c.1400C>T; p.Ser467Leu) mutation, one (6.2%) had an NRAS (c.385C>T; p.Gln129*) mutation, and rare EGFR, ERBB2, KRAS, and MET mutations were also exhibited in one sample (6.2%)." (PMID 28404952, 2017). "For example feedback activation of EGFR has been shown to cause intrinsic resistance to BRAF inhibition in colon cancer, and resistance to BRAF inhibition in melanoma can be caused by reactivation of the MAPK pathway by RTKs, NRAS, or COT." (PMID 28145866, 2017). "Tregs express the EGFR under inflammatory conditions, as witnessed by elevated levels of EGFR found on tumor-infiltrating Tregs derived from wild type (wt) mice with B16 melanomas, as well as EGFR expression on human Tregs with an activated phenotype of FoxP3hi and CD45RA-." (PMID 28970798, 2017). "Indeed, lapatinib, a clinical ERBB2 and EGFR inhibitor, effectively inhibited the ERBB3/ERBB2 pathway and importantly, delayed melanoma tumor growth in both mutated and wild type BRAF cells." (PMID 28060735, 2017). "There are multiple examples of oncogenic mutations that predict benefit from FDA-approved targeted therapies (CML/imatinib, melanoma/BRAFi, lung/EGFR and ALK inhibitors, breast/HER2 inhibitors), and other mutations that predict resistance (RAS mutations and EGFR inhibitors)." (PMID 27776519, 2016). "Another important question is whether miR-7 reverses the resistance to BRAFi in melanoma by modulating the expression of EGFR/IGF-1R/CRAF and the activity of their down-stream signaling pathways." (PMID 27448964, 2016). "The collective data suggested that co-inhibition of EGFR/IGF-1R/CRAF could decrease VemR A375 melanoma cell proliferation to a certain extent through the suppression of the activation of MAPK and/or PI3K/AKT signaling pathways." (PMID 27448964, 2016). "EGFR is significantly expressed in melanoma cell lines with the exception of one." (PMID 27102439, 2016). "Because IGF-1R, FGFR1, and EGFR have been shown to play major roles in melanoma progression through autocrine signaling, and EGF-R, PDGFRβ, and IGF-1R have been implicated in resistance mechanisms to BRAF V600E targeted therapies, we were interested in validating these results." (PMID 27102439, 2016). "Therefore, a further understanding of the underlying mechanisms and different roles of EGFR, IGF-1R and CRAF in BRAFi-resistant melanoma is a necessity." (PMID 27448964, 2016). "However, also low MITF/AXL and MITF/EGFR ratios have been suggested to be involved in early resistance to vemurafenib in a subset of melanomas." (PMID 27391157, 2016). "The first study hypothesized that increased EGFR could be the result of an adaptive response of melanoma cells occurring in presence of the drug and due to the activation of TGFβ signaling following loss of the transcription factor SOX10." (PMID 25742786, 2015).
melanoma (continued). "In addition to MAPK-ERK, PI3K-AKT and EGFR signaling, WNT5A signaling has also been implicated in melanoma resistance to BRAFi therapy." (PMID 26393652, 2015). "The ability of WNT5A to inhibit MITF, a downstream target of β-catenin, may be one cause of resistance in BRAFi-treated melanoma patients, as MITF depletion can activate EGFR signaling, which can confer BRAFi resistance." (PMID 26393652, 2015). "This fish EGFR is termed Xiphophorus melanoma receptor kinase (Xmrk) and was identified in naturally occurring melanoma of Xiphophorus fishes, the first described animal model for melanoma." (PMID 26000250, 2015). "EGFR expression has been reported in up to 96% of primary melanomas and 90% of metastatic lesions." (PMID 26079945, 2015). "Among the well-documented melanoma associated pathways, PI3K/Akt signalling (sigPCCM = 58, sigPCLN = 76) along with MAPK signalling (sigPCCM = 44, sigPCLN = 58) and EGFR signalling (sigPCCM = 49, sigPCLN = 59) too shares genes with a significant number of pathways." (PMID 26558755, 2015). "EGFR has been involved in adaptive and acquired resistance of melanoma to BRAFi." (PMID 25742786, 2015). "Interestingly, these investigators had also observed that EGFR expression in BRAF mutant melanoma cells was surprisingly detrimental to their proliferative capacity, and was only tolerated in the context of BRAF inhibition." (PMID 25031620, 2014). "In this scenario, the lessons learned from metronomic treatment strategies for BRAF V600E melanomas as well as EGFR-mutant NSCLCs suggest that discontinuous dosing of the drug could be a strategy to prevent or retard acquired resistance." (PMID 24811491, 2014). "The role of SOX10 in regulating EGFR in melanoma was further supported by the discovery of an inverse relationship between SOX10 and EGFR gene expression in a panel of BRAF mutant melanoma cell lines, as well as in a few BRAF mutant melanoma patient samples following treatment-associated resistance." (PMID 25031620, 2014). "Indeed, they found that post-treatment melanoma biopsies revealed evidence of increased EGFR expression." (PMID 25031620, 2014). "This is perhaps best exemplified by BRAFV600E mutations, which are predictive of response to Vemurafenib in melanoma, however colorectal cancer patients harboring oncogenic BRAFV600E mutations derive limited if any benefit from this drug due to increased EGFR expression." (PMID 22970424, 2012). "For instance, our Bio-LDA model suggested that there might be protein protein-protein interactions between CCND1 and EGFR, since both of them are important targets in the tumor related diseases: Carcinoma and Melanoma." (PMID 21448266, 2011). "The melanoma cell line A375 reportedly expresses human EGFR and responds to addition of EGF." (PMID 20663135, 2010). "Further investigation is needed of the application of EGFR targeted therapies to melanoma." (PMID 24281094, 2010). "Further, murine melanoma B16 cells express comparable EGFR to that found in A431 cells." (PMID 21176167, 2010). "Gained therapies included tyrosine kinase inhibitors (TKIs) in the context of EGFR-mutated NSCLC, trastuzumab deruxtecan for ERBB2-mutated NSCLC, ivosidenib for IDH1-mutated CCA, MEK and RAF inhibitor combination therapies for BRAF V600E melanomas, and PARP inhibitors for BRCA2-mutated HGSOC." (PMID 40399445, 2025). "Surprisingly, EAI045 completely blocked EGF-mediated phosphorylation of T790M/L848R and T790M/C797S/L858R, but just slightly decreased pAkt levels, suggesting that these two mutants may enhance pAkt independently of the phosphorylation of EGFR at tyrosine 1173, at least in these melanoma cells." (PMID 40649937, 2025). "We assume that NC and NC-CC ingredients that can inhibit malignant melanoma proliferation include medium-chain fatty acids which have been shown to enhance immune responses and induce apoptosis in cancer cells through activation of the EGFR/ERK/AP1 signaling pathway." (PMID 39770908, 2024).
melanoma (continued). "Mutations found in melanomas on the dorsal hand and foot were reported to be similar to those in melanomas at other sites of intermittently sun-damaged skin, whereas subungual and interdigital melanomas (n = 13) exhibited diverse mutations in PIK3CA, STK11, EGFR, FGFR3, and PTPN11." (PMID 36983205, 2023). "Thus, targeting Axl, in addition to other growth factor signaling pathways (including Braf and EGFR) could improve therapy aimed at preventing melanomas from metastasizing and generating lethal tumors." (PMID 36989239, 2023). "In the present study, we chose melanoma cell line WM983A to investigate the biological function of parental and mutant EGFR, as a prelude to whether this can be targeted in those patients with EGFR mutations." (PMID 37333807, 2023). "Therefore, the authors hypothesized that KIF22 might affect the proliferation and glycolysis of melanoma cells by regulating EGFR/STAT3 signaling." (PMID 37944197, 2023). "In malignant melanoma, the high level of AXL is mostly associated with the mesenchymal cell state, leading to enhanced resistance to targeted therapy, such as MAPK inhibitors in the case of malignant melanoma and endothelial growth factor receptor (EGFR) inhibitors in case of lung cancer." (PMID 37370757, 2023). "In some cancers where there is a mutant kinase driving the proliferation of the tumor cell by activating the MAPK pathway, such as mutant EGFR in NSCLC or BRAF(V600E) melanoma, vertical pathway combination kinase inhibitors maybe successful therapies in some patients." (PMID 34958800, 2022). "There is growing evidence, however, that β-catenin activation may occur through cues other than those involved in Wnt signaling, for example, the epidermal growth factor receptor (EGFR) in melanoma and the androgen receptor (AR) in prostate cancer, which was found to be a target of Wnt." (PMID 36497192, 2022). "EGFR inhibitors are classified into two major groups: the first with monoclonal antibodies, such as cetuximab and panitumumab, and the second with small molecule tyrosine kinase inhibitors that showed different efficacy towards melanoma cells as reported in preclinical and clinical studies." (PMID 33918490, 2021). "However, IL-24 molecular mechanisms and signaling pathways underlying melanoma suppression were not described and even less in combination with EGFR targeted therapy." (PMID 33918490, 2021). "Interestingly, miR-7 could reverse vemurafenib resistance in melanoma cell lines that overexpress EGFR, IGF-1R, and CRAF." (PMID 34948154, 2021). "Additionally, whether the effects of RA exerts in the progression of melanoma is related to EGFR/AKT signaling was explored." (PMID 34224305, 2021). "Interestingly, EGFR/STAT signaling may differ in human melanoma versus Xiphophorus Xmrk models since inhibition of c-Src kinase activity, but not EGFR, in human melanoma-derived cell lines, downregulates STAT3 signaling and Bcl-xL expression." (PMID 34067095, 2021). "However, if expressed, EGFR correlates with melanoma invasiveness and pro-metastatic features." (PMID 33916908, 2021). "Furthermore, the activation of the non-genomic pathway, via the combination of the epidermal growth factor receptor (EGFR) and AR, enhanced AR activity itself and modified the melanoma-associated antigen protein-A11 (MAGE-A11), improving melanoma proliferation." (PMID 32645881, 2020). "Indeed, SphK1 inhibition by the immunomodulator FTY720, which is also a functional antagonist of S1P receptors, downregulated the PI3K/AKT/mTOR signaling pathways and EGFR expression in SK-Mel-28 and A375 human melanoma cells, resulting in an increased sensitivity to cisplatin." (PMID 33121001, 2020). "Notably, semaphorin-NRP1 signaling is not involved in sustaining cell viability, and we have previously shown that VEGF-NRP1 autocrine signaling is not implicated in the pathway leading to EGFR upregulation and drug resistance in melanoma cells." (PMID 32784465, 2020).
melanoma (continued). "Interestingly, we could also observe in melanoma cells that NRF2 positively regulates EGFR and therefore strengthens the dedifferentiated phenotype by simultaneously suppressing MITF activity and inducing EGFR expression." (PMID 32978520, 2020). "Thus, we can speculate that FLG may also play an important role in the melanoma progression as well as EGFR." (PMID 33178610, 2020). "Finally, EGFR-high melanoma cells were characterized by higher PD-L1 expression, which might in turn indicate that immunotherapy may be an effective approach in these cases." (PMID 31514305, 2019). "It has been reported that EGFR is highly-expressed in melanoma, and its expression level is positively correlated with tumor progression and poor prognosis, hence it might be a useful target to inhibit melanoma via inhibiting the expression of EGFR." (PMID 30513793, 2018). "We compared the expressions of EGFR, VEGFA, and HIF1A in a subset of patients that included the 30 patients with thyroid cancer and 32 patients with melanoma for whom expression data was available." (PMID 40869231, 2025). "Our study demonstrates for the first time that sequential administration of DTIC, followed by EGFR mCAR T cell infusion after CPA pre-conditioning, results in significant antitumor efficacy in a syngeneic melanoma model." (PMID 41516067, 2025). "In melanoma, SPINK6 activates the EGFR/EphA2 complex and downstream ERK1/2 and AKT pathways, thereby promoting tumor metastasis." (PMID 39990675, 2025). "According to many reports indicating that drug resistance is often accompanied by overexpression of receptor tyrosine kinases (RTKs), the expression levels of EGFR, HER2, HER3, MET, and PDGFRβ receptors were verified in both resistant melanoma cell lines." (PMID 39175042, 2024). "The qPCR analysis revealed increased expression of EGFR (HER1) and HER2 in both resistant melanoma cell lines in comparison to the control ones." (PMID 39175042, 2024). "Treatment with rosmarinic acid dramatically reduced melanoma cell viability, proliferation, migratory, invasive, and chemotherapy sensitivity by inhibiting ADAM17/EGFR/AKT/GSK3β." (PMID 38398617, 2024). "ZEB1 binding peaks were also found in other major markers of melanoma cell identity, namely BIRC3, ITGA2 and EGFR, which are up-regulated upon phenotype switching towards the ZEB1high state as confirmed by RT-qPCR." (PMID 38519642, 2024). "For example, in the A375R melanoma cell line, METTL3 promotes methylation of the epidermal growth factor receptor (EGFR), thereby enhancing its translation and facilitating the rebound activation of the ERK pathway, which is associated with chemoresistance." (PMID 38444581, 2024). "Herbacetin also blocked the EGFR signaling pathway, which phosphorylated ERK and AKT to reduce melanoma cell angiogenesis." (PMID 38398617, 2024). "While HFF-1 showed higher levels of EGFR (p = 0.001) and JAK-3 (p = 0.001) genes compared to MeWo, the melanoma cell line presented higher expression of ERBB2 (p = 0.001), and ITK (p = 0.04)." (PMID 38790974, 2024). "The uPAR connection with EGFR (Epidermal Growth Factor Receptor) and the PI3K/mTOR/HIF pathway drives a glycolytic phenotype in melanoma." (PMID 38339003, 2024). "In melanoma, IGFBP2 plays additional roles in the activation of the Epidermal Growth Factor Receptor (EGFR)-Signal Transducer adn Activator of Transcripton (STAT3) pathway, activating Programmed Death Ligand 1 (PDL1), and contributing to angiogenesis." (PMID 39007351, 2024). "Cells representing two commercially available mucosal melanoma cell lines (GAK and HMVII) and one cell line obtained from a patient's vaginal melanoma were treated with MET or EGFR inhibitors, or combinations of these agents." (PMID 37679999, 2023).